HK2 (hexokinase 2)
Diseases named in the same sentence as HK2 in open-access papers (continued):
Sharing a sentence is not in itself a finding about the gene and the disease.
cancer (continued). "However, when HK2 expression is enhanced in cancer cells, glycolysis and mitochondrial energy production are both reduced." (PMID 34026612, 2021). "HK2, one example of hexokinases isoforms, is highly expressed in cancer cells." (PMID 34207699, 2021). "Of note, forced overexpression of HK2 induces cancer cell invasiveness, EMT, and cancer stemness." (PMID 34174908, 2021). "Consequently, silencing of these miRNAs in CC tissues stimulates the expression of HK2, facilitating the development of cancer stem cell-like properties and CDDP resistance." (PMID 34858863, 2021). "It is therefore possible to envision that MAM localization of HK2 could contribute to specific processes required for the fitness of cancer cells, such as the tight maintenance of intracellular and mitochondrial Ca2+ homeostasis." (PMID 33946854, 2021). "HK2 is the isoform expressed in cancer cells and regulates the first step in glycolysis." (PMID 34771733, 2021). "We have uncovered a previously unknown miR-148a/HK2 axis that modulates cancer stem cell-like features and CDDP resistance in CC." (PMID 34858863, 2021). "In addition to regulating glucose metabolism, HK2 promotes cancer stem cell self-renewal in CC cells, elucidating that HK2 is an upstream activator of cancer stem cell expansion." (PMID 34858863, 2021). "Targeting HK2 using HK2 inhibitors has been a hopeful strategy for cancer treatment." (PMID 34858863, 2021). "It has been shown that miR-143 inhibits HK2 expression and thus influences cancer metabolism." (PMID 34158025, 2021). "Besides, in metabolism-reprogrammed TME, decreased expressions of GLUT and HK2 impair activated TILs, and these metabolic changes correlate with increased Tregs and expression of PD-L1 and Galectin-9 on cancer cells." (PMID 34858835, 2021). "Targeting the NTD regulatory site will enable exploration of new families of potential HK2 inhibitors and could lead to design and development of novel and safe therapeutic interventions for the treatment of multiple cancer types." (PMID 33187984, 2021). "Hexokinase 2 (HK2) the rate limiting enzyme in glycolysis is often overexpressed in cancers." (PMID 34003246, 2021). "Given that high HK2 expression was detected in EC, we assumed that HK2 could exert oncogenic functions in this cancer." (PMID 34174908, 2021). "The PI3K/AKT/mTOR pathway facilitates the combination of HK2 and the outer mitochondrial membrane, which maintains a high metabolic rate, stemness, and promotes proliferation, invasion, metastasis, and chemoresistance of cancer." (PMID 34540667, 2021). "However, HK2 also maintains glycolysis in normal cells, which leads to the perplexity of inhibiting HK2 for cancer therapy." (PMID 34583722, 2021). "GLUT1, HK2 are the vital glycolysis enzymes regulating the glucose metabolic in cancer cell." (PMID 34868902, 2021). "Through physical interaction with its homologous partner SPIB, SPI1 is activated to promote aerobic glycolysis of cancer cells via upregulating HK2 or phosphoglycerate kinase 1 (PGK1), which in turn induces N2 polarization of neutrophils via glycolytic metabolite lactate." (PMID 34841706, 2021). "However, little is known about the functional role of HK2 in the maintenance of cancer stem cell-like ability and cisplatin resistance of CC cells." (PMID 34858863, 2021). "In addition to the catalytic activity of this enzyme, HK2 can also antagonize apoptosis within the mitochondrial pathway, which plays an important role in the invasion and metastasis of malignant tumors." (PMID 34217310, 2021). "Additionally, the correlation between aberrant HK2 expression and altered cell motility has been confirmed in many types of cancers, including pancreatic cancer, neuroblastoma, tongue squamous cell carcinoma, colon cancer, and breast cancer." (PMID 34758823, 2021). "Since hexokinase plays a vital role in the fate of glucose it is no surprise that changes in the expression of HK1 and HK2 have been linked to cancer phenotypes." (PMID 34158025, 2021).
cancer (continued). "HK2 binds to VDAC1 in the mitochondria to prevent apoptosis in cancer cells." (PMID 33802591, 2021). "In cancer, HK2 preferentially funnels glucose into aerobic glycolysis." (PMID 33627778, 2021). "MiR-125b recovers 5-FU and cisplatin sensitivity in various cancers by binding to HK2 mRNA." (PMID 34540667, 2021). "This may be due to the fact that HK2, instead of HK1, is frequently upregulated in cancer, and, in addition, the binding of HK2 to the external mitochondrial membrane in a complex with VDAC1 is known to contribute to fuel the glycolytic process." (PMID 34557403, 2021). "In addition to glycolysis modulation, HK2 is considered to regulate cancer progression by mediating intracellular apoptosis signalling cascades." (PMID 34378321, 2021). "In addition to its role in glucose metabolism regulation, HK2 has been reported to be overexpressed in multiple aggressive tumors and plays a key role in promoting cancer cell proliferation." (PMID 33753739, 2021). "Notably, HK2, and it is distinctly elevated in various cancers and contributes to aerobic glycolysis." (PMID 33442412, 2021). "The upregulation of HK2 in cancer is a major contributor to the elevated aerobic glycolysis and “Warburg effect” in cancer, and the low expression of HK2 in specific normal tissues makes it an attractive target for the selective inhibition of glucose metabolism in cancer." (PMID 33187984, 2021). "HK2 is an essential oncogene in human cancer and modulate the glycolysis in cancer." (PMID 32410389, 2020). "For example, hexokinase-2 (HK2), an enzyme that catalyses the conversion of glucose into glucose-6-phosphate, is overexpressed in a variety of cancers, has a promoting effect on the occurrence and development of CC, and is significantly related to the prognosis of patients." (PMID 33228592, 2020). "It was known that mitochondria‐bound HK2 conferred anti‐cell death ability to cancer cells." (PMID 31994339, 2020). "Accumulating studies have confirmed that HK2 expression was significantly up-regulated in a variety of malignant tumors, including PDAC, and it could directly promote metastasis via regulation of glycolysis." (PMID 32612951, 2020). "Recent studies have reported that STAT3 might play a crucial role in maintaining glycolysis in cancer cells by regulating HK2." (PMID 32273843, 2020). "Therefore, we examined the cancer cell-killing effect of the combination of HK2 ablation and metformin in vitro and in vivo." (PMID 32083006, 2020). "Highly proliferative cancer-like cells demonstrated increased glycolytic metabolism through the increased expression of hexokinase 2, and also, Akt activation plays a critical role in the activation of glycolysis through hexokinase activation in cellular proliferation." (PMID 32041182, 2020). "The association of HK2 with mitochondria and expression of pyruvate kinase PKM2 could promote effective yet uncontrolled energy distribution in cancer cells." (PMID 32509571, 2020). "HK (primarily HK2) is often overexpressed in many types of cancer and may represent a potential molecular target for therapy using flavonoids." (PMID 32843908, 2020). "Results from western blotting suggested that 10v could inhibit cancer transformation and progression via downregulation of HK2." (PMID 32843908, 2020). "Therefore, HK2 is regarded as a key player in aerobic glycolysis and has been proposed as a therapeutic target for cancers." (PMID 31918722, 2020). "Hexokinase 2 (HKII) is a tissue-specific isoenzyme that phosphorylates glucose to glucose-6-phosphate (G-6-P) at the start of the glycolysis pathway, and its upregulation contributes to cancer cell glycolysis and the Warburg effect." (PMID 30818878, 2019). "The expression of HK2 in cancer cells could be regulated at the transcriptional and post-transcriptional level." (PMID 30952834, 2019). "Importantly, increasing evidence support that high-level expression of HK2 is directly correlated with poor overall survival in cancer patients." (PMID 31607919, 2019).
cancer (continued). "Depletion of HK2 expression or treating cells with HK2 inhibitors could reverse the B7-H3-induced increase in aerobic glycolysis and B7-H3-endowed chemoresistance of cancer cells." (PMID 30952834, 2019). "This work uncovers that HectH9 is a novel regulator of HK2 and cancer metabolism." (PMID 31201299, 2019). "In addition, lonidamine, a derivative of indazole-3-carboxylic acid, can restrict cancer cell glucose metabolism by targeting HK2." (PMID 31607919, 2019). "Moreover, we have demonstrated that the induction of HK2 in cancer is partly due to CAF-CM-derived interleukin-6 (IL-6) activation, via its receptor IL-6R." (PMID 31212816, 2019). "Reducing HK2 expression can impede glycolysis and thus restrain cancer progression as well as HCC." (PMID 31137633, 2019). "The first rate-limiting enzyme of glycolysis is translocated to the outer membrane of mitochondria and interacts with the pore-like protein voltage-dependent anion channel (VDAC) to inhibit apoptosis, which is another mechanism for HK2 promoting the survival of cancer cell." (PMID 31137633, 2019). "Localization of HK2 on mitochondrial confers apoptosis resistance in human cancer cells." (PMID 31595166, 2019). "Exception from other hexokinase family members, HK2 is always overexpressed in human cancers." (PMID 31595166, 2019). "HK2 has been described as a target of the HIF1a protein in several cancers, including RCC." (PMID 31878355, 2019). "In cancer, hexokinase 2 (HK2) is often upregulated as a result of augmented glucose metabolism." (PMID 31027222, 2019). "Moreover, statistically higher HK2 immunoreactivity was detected in metastatic foci than their corresponding primary carcinomas." (PMID 31212816, 2019). "Future studies in regulation of HK1 expression in cancers and in normal tissues may provide targets for combination therapies in conjunction with HK2 inhibition for cancer treatment." (PMID 29988332, 2018). "However, the functional roles or effects of both HK1 and HK2 in glucose metabolism and the malignant progression of cancers are not fully understood, especially when their expression levels are decreased or low." (PMID 29721175, 2018). "Taken together, our findings suggest that the HK2 inhibition/DPI/PER combination is a potential precision therapeutic approach to treatments for cancers with the HK1−HK2+ characteristic existing in a broad spectrum of cancer types, regardless of their tissues of origin." (PMID 29988332, 2018). "Collectively, our data indicate that targeting HK2 may be a promising avenue for further research in cancer therapy, as it may spare T cell function while inhibiting cancer growth." (PMID 30140438, 2018). "The catalytic role of HK2 in glucose intracellular retention and metabolism is critical for cancer cells survival and proliferation, where its binding to the OMM provides a preferential access to mitochondrial ATP needed for catalysis and evades feedback inhibition by its products, G6P." (PMID 29298880, 2018). "Recent work has also shown that HK2 is required for angiogenesis, and this inhibition could theoretically further synergize with cancer cell HK2 inhibition to improve response to therapy." (PMID 30140438, 2018). "Consequently, selective HK2 inhibitors have recently been developed, under the assumption that targeted HK2 inhibition will reduce progression of HK2-positive cancers and have minimal adverse effects." (PMID 29988332, 2018). "HK2 is the only active HK isoform driving glycolysis in the HK1−HK2+ subsets of cancers." (PMID 29988332, 2018). "Furthermore, the up-regulation of HK2 has been shown to facilitate the chemotherapy resistance and metastasis in different cancer cells." (PMID 29298880, 2018).
cancer (continued). "In contrast, there was no significant synthetic lethality induced by the triple combination of shHK2/DPI/PER in HK1+HK2+ cancer cells, suggesting that our shHK2/DPI/PER triple-combination treatment is selectively cytotoxic for HK1−HK2+ cancer cells and is likely to be tolerated by normal tissues." (PMID 29988332, 2018). "The mitochondria binding of HK2 is also important to suppress apoptosis and cancer cell death." (PMID 29298880, 2018). "Moreover, evidence is mounting that binding of HK2 to VDAC plays a pivotal role in highly malignant cancer cells in promoting cell growth and survival." (PMID 30261663, 2018). "In addition, HK2 is expressed in a wide range of cancers, from tissues that normally express only HK1." (PMID 29988332, 2018). "Thus, either HK1 or HK2 overexpression in tumors is thought to provide both a metabolic benefit and an anti-apoptotic capacity that give the cancer cells a growth advantage and increase their resistance to anticancer therapy." (PMID 29721175, 2018). "Both HK1 and HK2 drive cancer aerobic glycolysis—glucose consumption and lactic acid production." (PMID 29988332, 2018). "Besides several studies demonstrating its ability to induce apoptosis, to arrest cell cycle and suppress metastasis in many cancer cell types, it was reported that oroxylin A induces dissociation of HK2 from mitochoia in human breast carcinoma cell lines." (PMID 29682501, 2018). "The requirement for HK2 in various cancer models has been described previously." (PMID 30140438, 2018). "HK1 and HK2 expression in the Cancer Cell Line Encyclopedia dataset was analyzed." (PMID 29988332, 2018). "HK2 is a highly upregulated enzyme in cancer and in T cells." (PMID 30140438, 2018). "Our finding that HK2 function can be dispensed with for CD4 T cell function could come as welcome news to the cancer therapy field." (PMID 29352298, 2018). "There was an inverse correlation between the expression of HK1 and HK2 in human cancer cells." (PMID 29721175, 2018). "Hexokinase-2 (HK2), the first rate-limiting enzyme in the glycolytic pathway, is known to be up-regulated in many cancers, and its overexpression correlates with short progression-free survival, which may be associated with chemoresistance in EOC." (PMID 29867465, 2018). "HK2 is expressed in higher levels in cancer cells and is responsible for the accelerated glucose flux —a property that distinguishes cancer from normal cells and was exploited for non-invasive visualization of cancer cells using 18F-fluorodeoxyglucose and positron emission tomography, FDG-PET." (PMID 30332737, 2018). "Thus, it is of high interest to identify cellular factors that stimulate HK2 expression and thereby induce the metabolic switch towards aerobic glycolysis in cancer cells." (PMID 29290953, 2017). "We focused our study on HK2-glucose link because of its critical role in cancer metabolism." (PMID 29137232, 2017). "It is assumed that cancer cells benefit from increased HK2 expression by various means." (PMID 29290953, 2017). "However, only Hexokinases II (HK2) is predominantly expressed in malignant tumors and are critical for maintaining an elevated rate of aerobic glycolysis in cancer cells." (PMID 28427230, 2017). "Hexokinases II (HK2) is a hub in the regulation of cancer cell glycolysis." (PMID 28427230, 2017). "Previous studies revealed that shutting down glucose flux at the earliest step in glucose metabolism by targeting HK2 could be an ideal strategy for cancer therapy." (PMID 28427443, 2017). "HK2 is only expressed in adipose tissue, skeletal muscle, and myocardium of normal human body at low level, but it is highly expressed in embryonic tissues and is the main isoenzyme type in cancer cells." (PMID 28009990, 2017). "Moreover, the expression level of HK2 distinguishes cancer cells from normal cells, which provides exciting opportunities for the development of therapeutic strategies to preferentially kill cancer cells." (PMID 28427443, 2017).
cancer (continued). "In summary, our findings demonstrate for the first time that hypoxia-down-regulated miR-125a regulated HCC glycolysis and carcinogenesis by targeting hexokinase HK2, a key glycolytic enzyme for the Warburg effect, and add a new dimension to hypoxia-mediated regulation of cancer metabolism." (PMID 28596599, 2017). "Hexokinase 2 (HK2), an isoform of hexokinase, catalyzes the first irreversible step of the glycolysis and helps couple ATP formation in mitochondria to glucose phosphorylation, resulting in cancer cell growth, survival and metastasis." (PMID 28445971, 2017). "Among those isoenzymes of Hexokinase, Hexokinase2 (HK2) has the closest relationship with cancer." (PMID 28009990, 2017). "Knockdown of HK2 by siRNA attenuated the promotion of IL-22 on glucose consumption and lactate production, indicating that HK2 is a functional downstream target of IL-22 in facilitating aerobic glycolysis of cancer cells." (PMID 28445985, 2017). "Third, HK2 can interact with Akt/mTOR signaling pathway, regulating the growth of cancer cells." (PMID 28009990, 2017). "Given the importance of HK2 in reprogramming glucose metabolism in cancer cells, we were interested in whether glucose metabolism was regulated by miR-125 and miR-143." (PMID 29156804, 2017). "HK2 expression is limited in most normal tissues but preferentially upregulated in cancer cells." (PMID 28915575, 2017). "This evidence suggests that inhibition of both HK2 and HK2-mediated glycolysis dysfunction might improve efficacy for cancer treatment." (PMID 28427230, 2017). "Our data uncovered a previously unknown mechanism of deguelin-induced cancer cells death and implies that HK2 offers a candidate molecular target for NSCLC therapy." (PMID 28427230, 2017). "Moreover, immunofluorescence revealed that the elevated HK2 was mainly localized in the cytoplasm of cancer cells, which is the primary worksites of HK2." (PMID 28445985, 2017). "Because PKM2 is an essential enzyme for regulation of aerobic glycolysis in cancer cells, we further determine that NEK2 expression is increased in high-risk patients and positively correlates with aerobic glycolysis genes including HK2, ENO1, and LDHA." (PMID 28086949, 2017). "In addition, due to its role in aerobic glycolysis in cancers, HK2 has been extensively investigated." (PMID 29043013, 2017). "All these studies confirmed that HK2 promoted the progression of cancers." (PMID 29043013, 2017). "Recent studies have suggested that EBV LMP1 may mediate energy metabolism reprogramming in EBV-infected cancer cells, including alterations in aerobic glycolysis, by activating the expression of specific metabolic enzymes, such as hexokinase 2 (HK2)." (PMID 28732079, 2017). "It has been reported that miR-143 could regulate glycolysis in cancer cells by targeting the first rate-limiting enzyme hexokinase 2 (HK2)." (PMID 26934324, 2016). "Specifically, HK2 has been suggested to contribute to the increased glycolysis by catalyzing the conversion from glucose to glucose-6-phosphate in the glycolytic pathway of cancer cells." (PMID 27824926, 2016). "HK2 expression is limited in most normal tissues, but frequently up-regulated in cancer." (PMID 28105937, 2016). "Since GLUT1 and HK2 are critical enzymes involved in reprogramming of glucose metabolism in cancer cells, we next sought to determine whether GLUT1 and HK2 are directly regulated by FOXM1 in EOC cells." (PMID 27351131, 2016). "Our results suggest that HK1 and HK2 could be the key therapeutic targets for reducing aerobic glycolysis in examined cancers." (PMID 28105937, 2016). "By targeting HK2, miR-143 reduces glucose metabolism and inhibits cancer cell proliferation." (PMID 26934324, 2016). "Recent studies report that either the level of hK2 alone or in combination with total PSA (tPSA) or free PSA (fPSA) might improve prediction of PCa stage and risk of biochemical cancer recurrence after radical prostatectomy (RP)." (PMID 26007739, 2015).